ALB (albumin)
Diseases named in the same sentence as ALB in open-access papers (continued):
Sharing a sentence is not in itself a finding about the gene and the disease.
liver disease (continued). "In cases where albumin synthesis is decreased secondary to concurrent liver disease, as in our case, a steady state of renal protein excretion may be reached at a lower threshold than 3.5g/24h despite severe defects in glomerular permeability." (PMID 39131015, 2024). "Similarly, the European Association for the Study of the Liver also recommends that all patients with SBP be treated with albumin on days one to three of hospitalization in an effort to curtail the development of hepatorenal syndrome." (PMID 38899040, 2024). "Consequently, the oscillating serum albumin levels serve as pivotal indicators, shedding light on the severity, progression, and prognosis of liver disorders." (PMID 37895045, 2023). "In the multivariate analysis, larger tumor size, multinodularity, older age, male, higher alpha‐fetoprotein (AFP), higher albumin‐bilirubin (ALBI) grade, and the presence of portal hypertension were significantly associated with higher recurrence and decreased survival rates." (PMID 36016484, 2023). "Additionally, some other growth factors (such as IGF-1) in PRP were reported to promote protein synthesis and increase serum albumin and total protein levels in some liver diseases or injuries." (PMID 37590313, 2023). "Fifth, the levels of the liver enzymes, albumin and bilirubin may also be affected by health conditions other than liver diseases." (PMID 37987396, 2023). "A low serum albumin can indicate poor prognosis in patients with liver diseases." (PMID 36675764, 2023). "Routine liver function tests such as: ALT, AST, serum creatinine, and albumin performed poorly in the surveillance mode and early detection of liver disease progression; however, serum total bilirubin gave somewhat useful guide for discrimination between fibrotic, cirrhotic and HCC patients." (PMID 37798688, 2023). "In fact, serum albumin levels may also be influenced by various factors such as liver diseases and changes of intravascular volume." (PMID 37700304, 2023). "Symptomatic supportive treatment such as albumin infusion, the reduction of portal hypertension, or even prophylactic anticoagulation could be given after evaluation of the hemorrhage risk and systemic status." (PMID 36675764, 2023). "In line with histological analysis, the variation in ALT, ALP, GGT, TB and ALB could lead to a liver disease." (PMID 36831704, 2023). "Protein and albumin produced by the liver are indicators of liver disease." (PMID 37570342, 2023). "As indicators of liver function, TBIL and ALB were mainly used to assess whether there was liver disease or damage, with many influencing factors and little relationship with the occurrence and development of HCC." (PMID 37920165, 2023). "Specifically, the ascites and plasma albumin levels in the C–P stage are interrelated, and bleeding caused by portal hypertension seriously affects the C–P stage, while TIPS can improve the bleeding caused by portal hypertension." (PMID 35183265, 2022). "Group-wise analysis with binary logistic regression in this cohort (n = 484), detected total bilirubin and albumin as predictors for the development of significant liver disease (p-value = 0.006 and 0.042, respectively) when compared between the ALD and ALC groups." (PMID 36238273, 2022). "In liver disease, total protein and albumin levels can be decreased." (PMID 35469194, 2022). "Albumin was the only blood test that changed systematically during a three-month period, and it stabilized thereafter, which indicates the decrease in albumin reflects a minor radiation-induced liver disease." (PMID 36568208, 2022). "Consequently, albumin infusions are recommended in all international guidelines following large volume paracentesis, diagnosis of spontaneous bacterial peritonitis and hepatorenal syndrome." (PMID 35333783, 2022).
liver disease (continued). "Several factors have been identified to be associated with elevated serum AFP in patients with liver disease of chronic hepatitis C other than HCC, such as elevated ALT, decreased platelet count, lower albumin levels, older age, female gender, ethnicity, and advanced fibrosis." (PMID 36016291, 2022). "Evaluation of portal hypertension by assessment of blood results was performed in a considerable number of studies: a combination of albumin/ALT/INR score completed by clinical signs of advanced liver disease (spider naevi) results in excellent sensitivity for portal hypertension." (PMID 36117519, 2022). "Including more precise statements in SmPCs/PI based on laboratory parameters (such as albumin) or scores (e.g., the Child–Pugh score) to objectify the severity of liver disease may improve the clarity of SmPCs/PI and the safety of drug prescription." (PMID 35407541, 2022). "Using gene‐based burden testing, which adds together all variants within a single category (e.g. pLoF or missense), variants in ALB demonstrated associations with serum lipids, but no other markers of liver disease." (PMID 35474605, 2022). "Serum albumin has been widely used as a valuable marker and therapeutic agent in critically ill patients, including those with shock, hypovolemia, cancer, acute respiratory distress syndrome, liver disease, resuscitation, and PCAS." (PMID 36579497, 2022). "There are many therapeutic uses of albumin in liver diseases." (PMID 35686237, 2022). "Impaired albumin synthesis and function have been reported in many liver diseases, and low serum levels of albumin may be a useful indicator of LD." (PMID 36303554, 2022). "In patients with advanced liver disease, albumin levels are often low." (PMID 36147905, 2022). "Albumin and total bilirubin were excluded from the analysed variables, as they were already included in the Child–Pugh scoring system that was used to assess liver disease prognosis." (PMID 36189384, 2022). "Although low albumin levels, high bilirubin levels, male sex, and presence of advanced liver disease remained significant as predictors of DAA treatment failure, the other two factors (e.g. liver enzymes, HCV RNA level) previously found to be significant predictors did not." (PMID 36302828, 2022). "Second, before an operation, the CALLY index may be influenced by subtle factors including indolent infection, undetected liver disease, and an aging-related physiological decrease in serum albumin level." (PMID 36046647, 2022). "There have been several models created for both de novo HCC and HCC recurrence, with the more recent models using a combination of age, sex, decompensation, and laboratory values (platelet count, albumin, bilirubin), and liver disease etiology to predict both 5 and 10-year HCC incidence." (PMID 35142988, 2022). "However, hyperlipidemia, hepatic disease, and hyperuricemia were significantly more prone to occur in people with higher albumin levels." (PMID 34055818, 2021). "Many of the physiological alterations encountered in liver disease, including systemic inflammation, oxidative stress, elevated blood glucose, and elevated plasma fatty acids, compromise molecular integrity and/or binding capacity of albumin." (PMID 34836265, 2021). "Decreased drug binding in liver diseases may be due to a decrease in albumin concentration, the accumulation of endogenous inhibitors (e.g., bilirubin), or changes in albumin structure." (PMID 34638659, 2021). "In healthy people, about 70% of albumin remains in a reduced form, but the level of oxidised albumin can increase up to 70% in kidney and liver diseases or in other pathologies, as well as in athletes after intense physical training or during the aging process." (PMID 34638934, 2021). "It is quite notable serum ALB oxidation per se could be a factor that aggravates pathological status in liver diseases." (PMID 33804859, 2021).
liver disease (continued). "Patients diagnosed with hepatorenal syndrome (HRS-AKI) were treated with terlipressin plus albumin." (PMID 34640346, 2021). "The serum-ascites albumin gradient was high at 1.4 g/dL, which indicated portal hypertension." (PMID 34401316, 2021). "While ICU admission and albumin were recognized as predictors of short-term mortality, we identified some risk factors related to CDI severity, such as leukocytes, CRP and Atlas score, and to the liver disease—mainly Child–Pugh score and MELD." (PMID 34204307, 2021). "Collectively, the oxidized shift of serum ALB redox state, initiated by oxidative stress in liver diseases, would not only impair physicochemical properties of ALB, but exacerbate vascular oxidative stress and inflammation through a neutrophil oxidative burst and a cytokine storm." (PMID 33804859, 2021). "The mechanism for this specificity could also be related to B cell activation in addition to reduced albumin synthesis secondary to liver disease and poor nutrition." (PMID 31940353, 2020). "On the contrary, albumin infusion, noted as a volume expander, may increase portal pressure and induce rebleeding due to deteriorated pre-existing portal hypertension." (PMID 32576140, 2020). "Importantly, group determination was not influenced by the tumor status at the time of resection (BCLC), by the parameters of liver function such as bilirubin, albumin and INR estimation, or by the aetiology of the underlying liver disease." (PMID 33225916, 2020). "Therefore, a preoperative assessment of liver function tests would exclude confounding liver diseases as well as explaining a low preoperative albumin." (PMID 32664910, 2020). "The higher occurrence of NAO/albumin complexes in patients with liver disease might therefore reflect an inefficient removal process due to bypassing portal circulation." (PMID 30930689, 2019). "However, albumin is used in patients with refractory ascites to prevent the circulatory dysfunction syndrome following paracentesis, in the setting of hepatorenal syndrome and in case of infection, especially spontaneous bacterial peritonitis (SBP)." (PMID 31717529, 2019). "Indeed, NOA against albumin have been found in healthy individuals albeit in lower concentration than in patients with liver disease." (PMID 30930689, 2019). "High occurrence of NAO/albumin complexes in patients with liver disease might reflect a limited clearance capacity due to bypassing portal circulation." (PMID 30930689, 2019). "Moreover, significantly lower albumin concentrations were found in female (n = 187) compared to male (n = 306) patients with CF who had severe liver disease, pancreatic insufficiency and portal hypertension." (PMID 31216743, 2019). "Several studies identified ascites, low HDL-cholesterol, and liver disease severity as risk factors for AI; other reported risk factors include low cortisol-binding globulin, higher MELD score, and lower serum albumin." (PMID 31320899, 2019). "The MSCs transfusions can significantly reduce mortality rate, lower the end-stage liver disease scores, increase serum albumin and cholinesterase, and increase prothrombin activity and platelet counts, while decreasing alanine aminotransferase levels and serum total bilirubin." (PMID 31915446, 2019). "In diseased individuals with liver disease, low albumin levels and hypergammaglobulinemia may result in excessive unbound NAO that can be detected in sera." (PMID 30930689, 2019). "It was reported that albumin levels are decreased in liver disease." (PMID 31388500, 2019). "Recommendation 1: Initial investigation for potential liver disease should include bilirubin, albumin, alanine aminotransferase (ALT), alkaline phosphatase (ALP) and γ-glutamyltransferase (GGT), together with a full blood count if not already performed within the previous 12 months." (PMID 29122851, 2018).
liver disease (continued). "Albumin itself has a variety of important physiologic functions such as antioxidant effects, immunomodulation, and endothelial stabilization in addition to its traditional biologic and therapeutic role in liver disease attributed mainly to its oncotic effects." (PMID 30240398, 2018). "Furthermore, after adjusting for age, gender, albumin, hemoglobin, liver disease, renal disease, malignancy, bilirubin, WBC, BUN, APS III, SOFA, SIRS, RRT, temperature, and Elixhauser, the high RDW was associated with an increase in mortality." (PMID 30345313, 2018). "Baseline albumin and platelet counts were lower in F4 fibrosis in all liver disease etiologies." (PMID 29746540, 2018). "Conditions such as acidosis and hypoxia at birth can affect the bilirubin/albumin ratio for binding, whereas the presence of any type of liver disease or a metabolic or enzyme disorder will also affect the ability of the body to properly process bilirubin to the direct form to allow for excretion." (PMID 28778173, 2017). "Likewise, HCV RNA and albumin levels follow the same pattern of decline in the terminal stages of liver disease." (PMID 28503671, 2017). "In hepatorenal syndrome, all vasoconstrictors should include cotherapy with albumin." (PMID 28932401, 2017). "Instead of the whole protein, the N-terminal fragments of ALB might have the potential to be used as biomarkers of liver recovery in various liver diseases." (PMID 28060824, 2017). "Pre-albumin serum concentration is diminished in liver disease and may be falsely elevated in renal failure." (PMID 29308073, 2017). "It is striking that in contrast to the symptom domains, advanced liver disease (assessed through the surrogate marker of serum albumin) does not associate with perceived PBC‐quality of life." (PMID 27640331, 2016). "Pertinent fluid analyses revealed glucose 100 mg/dL, amylase 52 U/L, WBC 372/UL with 48% polymorphonuclear cells (PMNs) and 24% lymphocytes, total protein 4.2 g/dL, and albumin 2.1 g/dL giving a serum albumin ascites gradient of 1.5, consistent with portal hypertension or congestive heart failure." (PMID 26618012, 2015). "We examined how these associations might differ among those with various albumin and hemoglobin levels, which may be particularly relevant in PLWH given the high prevalence of liver disease and erythrocyte turnover." (PMID 26273478, 2015). "Severe liver disease decreases vitamin D hydroxylation and albumin and DBP production." (PMID 25906757, 2015). "Finally, treatment of hepatorenal syndrome with terlipressin and albumin also lead to an improvement of serum sodium concentration." (PMID 26237020, 2014). "Finally, albumin administration is most common in patients with the most severe liver disease including those with hepatorenal syndrome." (PMID 23349678, 2013). "The observed median values of the four immune analytes and the known cut point of 2.8 g/dL (used in the Child-Turcotte-Pugh scoring system for identifying subjects with severe [class C] liver disease) for albumin were used to dichotomize the continuous variables into binary variables." (PMID 24386086, 2013). "In addition, GGT, ALB, PLT, ALT and AST were all significantly associated with the presence of liver disease." (PMID 24260428, 2013). "The association between a low BMI and a low quality of life score was independent of the severity of the underlying liver disease, presence of ascites, and albumin level." (PMID 24490061, 2013). "Although the factors involved in cirrhotic ascites have been studied for a century, a number of observations are not understood, including the action of diuretics in the treatment of ascites and the ability of the plasma-ascitic albumin gradient to diagnose portal hypertension." (PMID 22453061, 2012). "Presumably, lower serum albumin in patients with non-alcoholic fatty liver disease could also be related to more advanced liver disease, higher degree of systemic inflammation, or albuminuria due to diabetic nephropathy." (PMID 21960993, 2012).
liver disease (continued). "However, it is important to underline that the same molecules increased in CHC and LC patients with the sole exception of HGF that can be used for predicting the progression to HCC in patients with CHC-related liver disease and low albumin." (PMID 22745767, 2012). "Furthermore, multivariate analysis showed that fibrosis was the only independent predictor for risk of HCC development after adjustment of age and other markers of advanced liver disease (Plt, Bil, albumin, INR AST, GGT)." (PMID 22044490, 2011). "MARS albumin dialysis therefore appears to be an effective treatment to allow recovery of liver function after severe intoxication or, in the case of more fulminant liver disease, bridge patients awaiting urgent liver transplantation." (PMID 16608508, 2006). "C-reactive protein (CRP)-to-albumin ratio (CAR), NAR, and NLR have been reported to be associated with poor liver function in patients with liver cirrhosis, and nutritional and inflammation-based indices may play a role in liver function in liver disease." (PMID 40747208, 2025). "Similarly, the CRP/albumin ratio has been recognized as a composite marker that captures both the inflammatory state and nutritional status, two key prognostic domains in advanced liver disease." (PMID 41590616, 2025). "Albumin is synthesized from amino acids in the liver, and its production and concentration in plasma may be reduced due to decreasing supply of precursor amino acids or liver diseases such as NAFLD." (PMID 41001124, 2025). "Human serum albumin levels may be affected by chronic renal or hepatic diseases." (PMID 38877408, 2024). "Thus, our findings were derived from a population not including individuals with a personal history of renal or liver disease, that may reduce serum albumin by enhancing its excretion or lowering its biosynthesis, respectively." (PMID 39010980, 2024). "Besides, deviations from normal range of laboratory results might result from prior diseases as well, especially decreased albumin and elevated liver enzymes from liver disease." (PMID 38411872, 2024). "Considering that albumin levels may be altered in advanced kidney failure, liver diseases, and cancer-related conditions, individuals who presented with disorders related to the urinary system and liver failure in the initial assessment were excluded from the study." (PMID 39797126, 2024). "In addition, we have not excluded patients with renal failure, which may have affected lactate and albumin clearance, albeit to a lesser extent than liver disease." (PMID 39272772, 2024). "Furthermore, advanced liver disease itself, characterized by higher liver disease severity scores, high hepatic venous pressure gradient, low serum albumin, and large-volume ascites and presence of neuropsychiatric manifestations of HE significantly impacts sexual function." (PMID 39610685, 2024). "In addition, the liver is the only site of albumin synthesis and decreased ALB concentrations in rabbits that may be associated with advanced hepatic diseases, such as hepatic coccidiosis or scarring and necrosis." (PMID 37104403, 2023). "Therefore, the CrCL and albumin covariates discovered in this study will be useful as indirect data for setting the zaltoprofen dose in healthy adults and patients with specific conditions, such as kidney or liver disease." (PMID 37259312, 2023). "However, the structural and functional integrity of the albumin molecule can be compromised by a series of influencing factors, including inflammation, oxidative stress, glycation, and diseases, such as liver disease." (PMID 37628734, 2023). "As multiple markers have demonstrated to be abnormal in patients with advanced liver disease compared with healthy volunteers, we sought to validate these markers by comparing levels in survivors and nonsurvivors at 3 months and then investigated the effect of targeted albumin infusions." (PMID 35333783, 2022).